IL4 (interleukin 4)
Diseases named in the same sentence as IL4 in open-access papers (continued):
Sharing a sentence is not in itself a finding about the gene and the disease.
cancer (continued). "Morphine decreased the cancer cell coculture- or IL-4-induced expression of arginase-1 in RAW264.7 or bone marrow derived macrophages." (PMID 26078009, 2015). "C4-27z and C4opt-27z CAR T lymphocytes secreted low, but reliably detectable levels of Th-2 cytokines, including IL-4 and IL-10, in response to FRα+ cancer cells although the response was considerably Th-1 biased." (PMID 26359629, 2015). "Specifically, IL-4-producing T cells are elevated in patients with cancers that parallel worse prognosis." (PMID 25208941, 2014). "The present meta-analysis, including 1583 cases and 1638 controls from 8 case–control studies, comprehensively assessed the association between IL-4 intron 3 VNTR polymorphism and risk of human cancers." (PMID 25484626, 2014). "The relationship between IL-4 intron 3 VNTR polymorphism and cancer risk was assessed and this polymorphism was associated with cancer risk, mainly in Asians." (PMID 25484626, 2014). "COX-2 expression decreases the sensitivity of cancer cells to activated antigen-specific T cells by inducing the expression of IL4 and IDO, and by modulating the release of interferon-gamma by activated T cells." (PMID 25501829, 2014). "Down-regulated genes such as MMP2, MAPK1, TBFRS7, REL A, SAFB, FES identified GO terms listed as TGF-beta signaling, angiogenesis, IL-4 signaling, cartilage development and cancer-related pathways." (PMID 24756038, 2014). "To date, several case–control studies have been carried out to explore the linkage between IL-4 intron 3 VNTR polymorphism and the risk of several human cancers." (PMID 25484626, 2014). "Interleukin-4(IL-4) is a critical inflammatory cytokine and has been involved in pathogenesis of cancer." (PMID 25484626, 2014). "These cancer cells produced interleukin-4 (IL-4), which amplified the expression levels of these antiapoptotic proteins and prevented cell death induced upon exposure to drug agents." (PMID 25328756, 2014). "IL-4 has also been demonstrated to protect other cancer cell types, such as breast, bladder, prostate and thyroid cancer cells, from apoptosis." (PMID 24728412, 2014). "To date, several studies have investigated the association between IL-4 intron 3 variable number of tandem repeats (VNTR) polymorphism and cancer risk in humans; however, the results remain controversial." (PMID 25484626, 2014). "Interleukin 4 (IL-4) is involved in the regulation of apoptosis and migration of macrophages in numerous cancers." (PMID 24278120, 2013). "Previous studies have suggested that IL-4 can promote proliferation of various cancer cells of different origin under nutrient depletion stress condition." (PMID 24339977, 2013). "Although the receptor for interleukin-4 (IL-4R) is highly expressed on solid human cancer cells, its internalization function is still unclear." (PMID 23029030, 2012). "MBS cytotoxicity and MBS-induced anticancer cytokines, TNF-α and IFN-β from cancer cells, and immunological cytokines, IL-4, IFN-γ, and IL-10 from peripheral mononuclear cells (PMNC) were assessed by MTS and ELISA assays." (PMID 23122182, 2012). "A paradoxical role of IL-4 in cancer progression began to emerge following work that was conducted using IL-4 knock-out mice." (PMID 24213139, 2011). "Following on from these findings, several small and early stage studies were performed to test the toxicity and therapeutic potential of IL-4 in patients with cancer." (PMID 24213139, 2011). "DC-vaccine therapy involves generating immature DCs in vitro by culturing peripheral blood monocytes with GMCSF and IL4, before exposing them to cancer-specific antigens and re-administration into the patient." (PMID 19997099, 2010). "Network 2 has TGFB1 and IL4 driving several genes known to be involved in cancer development but also known to negatively regulate potentially tissue destructive immune responses." (PMID 18267009, 2008).
cancer (continued). "We show here that, even in the presence of IL-4, differences in differentiation of circulating monocytes into DCs persisted in cancer patients as compared with healthy donors." (PMID 15987427, 2005). "This property of sharing of receptors for IL-4 and IL-13 has also been observed in other cancer cell lines and thus appears to be universal." (PMID 11870521, 2002). "Numerous cancer-related pathways can be activated by IL-4 generated by Th2 cells." (PMID 38231074, 2025). "Moreover, IL-4 secreted by cancer cells can mediate resistance to immune checkpoint blockade (ICB) therapies, reducing the efficacy of treatments such as PD-1/PD-L1 inhibitors." (PMID 40864740, 2025). "Collectively, these findings may guide the development of improved personalized cancer therapeutics that harness the IFN-I/IL-4 axis to reinvigorate antitumor T cell responses against solid tumors." (PMID 40367186, 2025). "In contrast, recombinant IL-4 potentiated type 1 immunity to eliminate cancer." (PMID 39744952, 2025). "The role of IL-4 signalling in multiple cancer types, including GBM, is widely documented." (PMID 41029387, 2025). "In addition to the standard cytokines, other molecules, such as IL-4, IL-9, and IL-24, are of research interest; they seem to act at different levels of the anti-cancer immune axis." (PMID 40722601, 2025). "Neither stress nor cancer caused any significant changes in IL‐2 or IL‐4 concentrations in the mouse brain." (PMID 40172096, 2025). "PD-L1 is commonly expressed on T-cells, B-cells, macrophages, cancer cells, and DCs and is upregulated through the release of pro-tumor cytokines (such as interleukin-4 (IL-4), IL-10, and vascular endothelial growth factor (VEGF)) from cancer cells and is associated with poor prognosis." (PMID 40356923, 2025). "Pathway analysis predicted IL4 activation in the cancer compartment in PNI." (PMID 40075699, 2025). "In environments characterized by hormone-resistant prostate cancer, research indicates that increased IL-4 levels substantially boost the clonogenic capacity of cancer stem cell-like entities and augment the proliferation of androgen-sensitive LNCaP cells via IL-4 overexpression." (PMID 39678517, 2024). "Increased Th2 cells promote cancer growth and metastasis by producing IL-4, IL-5, and IL-10." (PMID 38293522, 2024). "IL-4’s functional and biological roles have been extensively studied across various cancer types." (PMID 39334861, 2024). "Additionally, cytokines namely IL-4 and IL-13, secreted by Th2 cells, promote cancer progression by inducing polarization of M2 macrophages." (PMID 39726600, 2024). "In the TME, IL-4 may support the proliferation of Tregs and M2 macrophages, which encourage cancer progression and immunosuppression." (PMID 39727942, 2024). "However, it is widely accepted that this binary classification of macrophages on anti-cancer M1 and pro-cancer M2 is oversimplified and can be seen only in vitro as a result of stimulation of activated monocytes with bacterial LPS/IFNγ or IL-4." (PMID 38794298, 2024). "Two analyzed cytokines, IL-1β and IL-4, are known for their pleiotropic effects in cancer." (PMID 38835768, 2024). "In addition, it would be necessary to characterize immune cells in the TME and how they respond to modulation of the IL4 receptors, as well as the signaling consequences of targeting IL4 in cancer cells themselves." (PMID 38731867, 2024). "Similarly, exposure of macrophages to IL-4 secretion from Th2 cells or cancer cells results in their alternate activation or M2 polarization." (PMID 39260692, 2024). "Several research endeavors have indicated the possible involvement of IL-4, IL-10, and IL-13 in mitigating the aggressive characteristics of cancer within bone structures, underscoring their viability as pharmacological targets for the management of bone metastases." (PMID 39125732, 2024). "IL-4 and IL-10 cytokines are upregulated in premalignant and cancer lesions." (PMID 39599846, 2024).
cancer (continued). "IL-4 produced by Th2 cells has been shown to activate a number of cancer-related pathways." (PMID 38722372, 2024). "Among which, IL-4 has been connected to various cancer types as the main inflammatory cytokine." (PMID 36619680, 2023). "It was concluded that the cancer cell spheroid secretome is affected by IFNγ/Pam3SCK4 and IL-4." (PMID 37445941, 2023). "However, it was shown that in established PDA, cancer cells can also be a source of IL-4 to further increase the alternative macrophage population." (PMID 37638028, 2023). "In addition, it’s well known that Th2 cells contribute to cancer progression and metastasis by secreting IL-4, IL-5, IL-10 and IL-13." (PMID 37950236, 2023). "This kind of IL-4 superkine was aimed to be used as a super agonist to treat cancer." (PMID 36936961, 2023). "It is theoretically possible that a leaky amount of activation factors (IL4, or IFNγ/Pam3SCK4) are present in the (w/o) macrophage environment and may interact with the cancer cell spheroid." (PMID 37445941, 2023). "IL-4 promotes RA development via cytokine–receptor interaction, Th1 and Th2 cell differentiation, Th17 cell differentiation, T-cell receptor signaling pathway, cancer pathways, and hematopoietic cell lineage; curiously, IL-4 gene expression is lower in women with RA than in men." (PMID 38202062, 2023). "Additionally, when tested in a DC/iNKT cell model, certain cancer cell extracts have been shown to induce an increase in IL-4 levels." (PMID 37444608, 2023). "However, cancer patients before treatment had higher levels of inflammatory cytokines such as IL‐2, IL‐4, IL‐6, IL‐8, and IL‐10 than healthy controls and performed worse on cognitive tests." (PMID 36965094, 2023). "Furthermore, some studies indicate that cancer cells have the ability to stimulate Th2-type cytokines, including IL-4, to evade the immune system." (PMID 37444608, 2023). "Here, several tests were performed to assess (i) the impacts of BAM15 on lipopolysaccharide (LPS)-induced M1 polarization or M2 polarization (using IL-4 and cancer cell supernatant) and (ii) the influence of BAM15-PLGA particles (BAM15 particles) on macrophages and in mice." (PMID 38140036, 2023). "Cytokines of the intestinal microenvironment dominate immunological responses, and therefore the abnormalities in the expression of cytokines, like IL-4, and IFN-γ, mirror the dysregulation of intestinal immunity associated with pathological processes, including cancer." (PMID 37532996, 2023). "Increased IL-4 levels have been frequently observed in various types of cancers." (PMID 38022654, 2023). "In cancer, however, IL-4 was originally used as an immunotherapeutic drug against malignant tumors." (PMID 36936961, 2023). "IL4 can induce 3β-HSD activity in various types of human cancer cells." (PMID 36362361, 2022). "Research data indicated that IL-4 could potentially stimulate stemness genes and CSC survival, which were associated with cancer metastasis, recurrence, and drug-resistance." (PMID 36466926, 2022). "IL4 protects cancer cells from cell death and chemotherapeutic drug-induced apoptosis." (PMID 36362361, 2022). "For instance, IL-4 improves myocardial repair and enhances function of damaged hearts through induction of M2-reparative macrophages; Clinical trials targeting IL-4 has also been demonstrated safe for cancer treatment." (PMID 36539414, 2022). "IL-4 and IL-13, secreted by activated Th2 cells, induce aberrant expression of activation-induced cytidine deaminase (AID), which can result in DNA mutations with potential cancer development." (PMID 34986892, 2022). "Interleukin-4 (IL-4) signaling, drug efflux proteins, and the upregulation of aldehyde dehydrogenase (ALDH) activity are all known to be associated with the resistance of CSCs to conventional cancer therapies." (PMID 36430659, 2022).
cancer (continued). "It has been reported that receptors for IL4 and IL13 (IL4Rα or IL13Rα1) in several type of cancers is associated with poor prognosis and thus could be therapeutic targets of cancer treatment." (PMID 35207737, 2022). "IL-4 and IL-6 secreted by cancer cells could promote the infiltration and M2 polarization of macrophages." (PMID 35864548, 2022). "The host-directed protective response is dependent on the Th2 cytokine interleukin-4 (IL-4), which indicates that type 2 immunity could be an effective tissue-level defense mechanism against cancer." (PMID 36589226, 2022). "Additionally, several cancer types express IL-4 and the IL-4R, which suggests a role in tumor progression cancer." (PMID 36172343, 2022). "Interleukin 4 (IL4) induces the expression of HSD3B1 in various human cancer cell lines." (PMID 36362361, 2022). "IL4 induction of HSD3B1 expression has been reported in several cancer cell lines." (PMID 36362361, 2022). "Besides the direct effect against cancer cells, xanthone 1 interferes with macrophage functions and increases its effectiveness against the metabolic viability of the cancer cell lines when stimulated with IL-4." (PMID 34207168, 2021). "IL-4 produced by Th2 cells can result in the activation of several cancer-related pathways." (PMID 35173766, 2021). "Blockade of IL-4 by antibody also attenuates LMSCs-driven cancer metastasis to the lungs." (PMID 34707103, 2021). "Furthermore, cancer-initiating cells isolated from CRC patients showed weak immunogenicity in vitro because of their membrane-bound IL-4." (PMID 33450900, 2021). "IL-4 can have anti-cancer properties, but it is largely immunosuppressive." (PMID 34177932, 2021). "Additionally, IL-4 also supports enhanced proliferation and survival of cancer cells in part by inducing glucose uptake." (PMID 34681866, 2021). "A new potential treatment modality for cancer could be dupilumab, an antibody targeting IL4Rα, a receptor subunit for IL4 and IL13." (PMID 34235145, 2021). "More and more evidence has been provided in recent years that interleukin-4 (IL-4), interleukin-13 (IL-13), and their receptors play an important role in cancer cell proliferation and other biological behaviors, such as migration and invasion enhancing the malignant phenotype." (PMID 33450900, 2021). "NK-4 exhibits a variety of biological activities, such as preventing IL-4-driven polarization to alternatively activated macrophages and inhibiting cancer cell proliferation, allergy, and inflammation, and thus has been used to treat cancer and virus infection." (PMID 34358120, 2021). "However, when macrophages were stimulated with IL-4, an increase in cytotoxicity against cancer cell lines was observed for supernatants of compound 1-treated macrophages (p < 0.05) compared to the control." (PMID 34207168, 2021). "Therefore, there is an increase in IL-4 mRNA and protein expression following treatment with either drug in all normal and cancer cell types investigated." (PMID 33321722, 2020). "It is not difficult to find that related genes in the interleukin-4 and interleukin-13 signaling pathways have decreased activity in cancer samples, and their associations have also been disrupted." (PMID 32832545, 2020). "Recently, a number of studies have focused on the relationship of IL-4 with cancer development." (PMID 32744314, 2020). "Transcriptional analysis of correlation patterns was conducted on clinical samples from CRC patients to reveal possible association between expression level of IL4, IL4Ra, IL13, and IL13Ra1 and that of representative mediators/markers associated with cancer development and progression." (PMID 32512917, 2020). "Also, in a variety of cancer cells, uPAR expression has been shown to induce, secretion of IL-4, via a mechanism that involves activation of ERK1/2, which, in turn, promotes M2 polarization of macrophages." (PMID 32344648, 2020). "Available literature on IL-13 in the GIT cancers is even scantier than that concerning IL-4." (PMID 32512917, 2020).
cancer (continued). "Along with cancer progression, following the “equilibrium” and “escape” phases of cancer immune-editing, tumor microenvironment elicits the alternative, M2, activation of TAMs, induced by the secretion of cytokines, such as IL-4 and IL-13, by Th2 cells, basophils, and eosinophils." (PMID 32650452, 2020). "However, IL-4-polarized macrophages from WT mice in combination with SM-164, slightly but significantly increased apoptosis of the cancer cells and decreased the total number of GFP+ cells." (PMID 32332865, 2020). "On the one hand, IL-4 has been more markedly elevated in patients with higher modified Glasgow Prognostic Score, thus with worse prognosis, but lower in those with more advanced cancers, that is, with vascular invasion or N3 cancers, on the other." (PMID 32512917, 2020). "As compared to controls, IL-4 was significantly elevated in all cancers." (PMID 32512917, 2020). "IL-4 and IL-13 per se exert a protumor function, since they directly bind to high-affinity receptors (IL-4Rα and IL-13Rα1 chains), forming functional receptors in cancer cells." (PMID 33233582, 2020). "IL-4 is reportedly conferring cancer cells protection against apoptosis." (PMID 32512917, 2020). "Indeed, future investigations are required to better understand the role of IL-4 in regulating Th2 and Th9 cells in adoptive immunotherapy for cancer." (PMID 30842774, 2019). "Thus, 4/21 ICR is promising to be an alternative design for next-generation CAR-T therapy in IL-4-rich cancers." (PMID 31379876, 2019). "Radiation induces the expression of the IL-4 gene in human carcinoma cells." (PMID 30813636, 2019). "As previous studies proved that IL-4 with high expression value promoted cancer stemness and predicted the poor prognosis in cancers, the results indicated that cancer stemness might depend on the interaction between TBX21 and IL-4 in LUAD cells." (PMID 29615105, 2018). "However, the associations of several other cytokines (IL-36γ, MIP-1β, RANTES, IP-10, IL-2, IL-4, Flt-3L, sCD40L) with cancer were dependent on the VMB composition." (PMID 29765068, 2018). "However, when treated with interleukin (IL-4) and IL-13, they are polarized to an immunosuppressive M2 phenotype and are involved in cancer progression." (PMID 30158589, 2018). "Interleukin 4 signaling supports cancer cell proliferation and survival." (PMID 30154786, 2018). "Furthermore, metformin treated cancer cells displayed inhibited secretion of IL-4, IL-10 and IL-13; cytokines important for inducing M2 macrophages." (PMID 28157701, 2017). "IL-4 increased the clonogenic potential of primary cancer cells." (PMID 28553931, 2017). "To examine whether human macrophages could phagocytize DNA derived from apoptotic cancer cells we differentiated human monocyte derived macrophages (hMDMs) into the M2 phenotype using IL-4." (PMID 29137267, 2017). "However, fractionation of these rare cell populations revealed that stem-like cells isolated from cancers have significantly higher expression levels of IL4Rα, suggesting a potential tumourigenic role for IL-4/IL4Rα in PCa CSCs." (PMID 28553931, 2017). "Hence, IL-4 has been seen as the focus of controversy in recent years due to the indeterminate biologic functions on cancers." (PMID 29137245, 2017). "It is well known that IL-4 and IL-13 play an important role in cancer development." (PMID 28893247, 2017). "In addition, we did not detect a difference in expression of the Th2 marker CCR4 but did observe decreased production of the Th2 effector IL-4 from CD4+ cells taken from cancer septic mice." (PMID 27018973, 2016). "IL-4 and IL-4Rα were also highly expressed in several types of cancer cells (right)." (PMID 27895317, 2016). "IL-4, as an autocrine factor, has a critical role for survival signals of cancer stem-like cells." (PMID 27895317, 2016). "IL-4 also promotes migration of cancer cells via the Akt/Stat6 pathway signaling." (PMID 27895317, 2016).